CYP20A1 (cytochrome P450 family 20 subfamily A member 1)
Synonyms: CYP-M
Tractability: Small molecule: it belongs to a druggable protein family. Antibody: UniProt predicts a signal peptide or a membrane-spanning region. PROTAC: ubiquitination databases record sites on it; its protein half-life has been measured.
Gene: Protein-coding gene on chromosome 2 (203,238,952 to 203,306,026, forward strand). Ensembl gene ENSG00000119004.
Subcellular location: Membrane
Subcellular location (Human Protein Atlas): Actin filaments; Cell Junctions; Plasma membrane; Nucleoplasm
Gene Ontology:
Molecular function: protein binding; heme binding; iron ion binding; monooxygenase activity; oxidoreductase activity, acting on paired donors, with incorporation or reduction of molecular oxygen
Cellular component: membrane
Genetic constraint (gnomAD): Loss-of-function variants: 28 observed, 23.77 expected, observed/expected ratio (o/e) 1.18, 90% interval 0.87 to 1.61. The upper end of that interval is the gene's LOEUF score, 1.61, which puts it in group 6 of 6, group 1 being the genes least tolerant of losing a copy. Missense variants: 285 observed, 293.18 expected, observed/expected ratio (o/e) 0.97, 90% interval 0.88 to 1.07. Synonymous variants: 106 observed, 106.66 expected, observed/expected ratio (o/e) 0.99, 90% interval 0.85 to 1.17.
Homologues: Orthologues: dog CYP20A1 (92% identical), pig CYP20A1 (91% identical), rabbit CYP20A1 (90% identical), guinea pig CYP20A1 (84% identical), mouse Cyp20a1 (83% identical), rat Cyp20a1 (82% identical), macaque CYP20A1 (78% identical), chimpanzee CYP20A1 (77% identical), tropical clawed frog cyp20a1 (72% identical), zebrafish cyp20a1 (63% identical).
Diseases named in the same sentence as CYP20A1 in open-access papers:
CYP20A1 is named in the same sentence as 25 diseases in open-access papers, as found by Europe PMC text mining. Sharing a sentence is not in itself a finding about the gene and the disease. The quoted sentences say what the papers report.
lung carcinoma (3 papers, 2017 to 2022). "Overexpressed CYP20A1 is observed in some pathological types of lung cancer and associated with prognosis according to a previous study." (PMID 35480120, 2022).
Anxiety (1 paper, 2021). Intense feelings of nervousness, tension, or panic often arise in response to interpersonal stresses. "Patients with chromosome 2 microdeletions including CYP20A1 show hyperactivity and bouts of anxiety, among other conditions." (PMID 34903767, 2021). "The resemblance in anxiety and hyperactivity responses between humans and zebrafish with deletions in the CYP20A1 locus suggests that our zebrafish cyp20a1-/- crispants can serve as a disease model organism." (PMID 34903767, 2021). "In all three trials, the cyp20a1-/- fish (wh61) spent more time in the bottom third of the novel tank, which is an indication of anxiety-like behavior." (PMID 34903767, 2021). "Adult cyp20a1 null fish showed a pronounced delay in adapting to new environments, which is consistent with an anxiety paradigm." (PMID 34903767, 2021).
chronic kidney disease (1 paper, 2022). Impairment of the renal function secondary to chronic kidney damage persisting for three or more months. "Seventeen-nucleotide tRF-3b can regulate Ca2+ ion transport by interacting with mRNA ORAI2 or CACNG proteins and modulating the activity of CYP20A1 and GAS7, proteins associated with kidney diseases, such as kidney nephropathy, proteinuria and chronic kidney disease." (PMID 35409004, 2022).
infertility disorder (1 paper, 2022). Inability to conceive for at least one year after trying and having unprotected sex. "This study provides evidence that an increase in CatSper, StAR, 3β-HSD, and CYP20A1 and downregulation of STAT3, COX-2, and associated signaling pathways can provide an effective strategy to prevent CDDP-induced reproductive toxicity and infertility disorders." (PMID 36290786, 2022).
large cell lung carcinoma (1 paper, 2019). "We found the expressions of CYP2D6 were significantly up‐regulated in large cell lung carcinoma, AC and SCC patients compared with the normal samples (P < 0.05), and CYP24A1 and CYP20A1 were found overexpressed in the AC (P < 0.05)." (PMID 31264381, 2019).
cancer (4 papers, 2023 to 2025). A tumor composed of atypical neoplastic, often pleomorphic cells that invade other tissues. "While the exact role of CYP20A1 in oncogenesis is unclear, changes in expression could potentially influence cancer progression through its involvement in metabolic pathways." (PMID 40867248, 2025). "Similarly, CYP4F3 and CYP20A1 were prominently expressed in advanced-stage HNSCC patient biopsies, indicating that the tumour microenvironment may upregulate these isoforms to support cancer progression." (PMID 41174467, 2025).
tumor (4 papers, 2019 to 2025). "CYP2S1 was significantly detected in T3 and T4 tumours, with a sequence coverage of 7% and a Mascot score of 88, while CYP20A1 was detected across pT2 and T4 tumours." (PMID 41174467, 2025). "CYP20A1 and TOMM6 influence tumor metabolism and response to stress." (PMID 40867248, 2025).
CYP20A1 also shares sentences with these, for which no sentence is quoted: infection (4 papers); colorectal cancer (2); fungal infection (2); kidney diseases (2); breast adenocarcinoma (1); cryptococcosis (1); geographic atrophy (1); Hashimoto thyroiditis (1); Hepatic steatosis (1); Insulin resistance (1); kidney adenocarcinoma (1); kidney nephropathy (1); leishmaniasis (1); liver fibrosis (1); Nephropathy (1); Obesity (1); ovarian carcinoma (1); pancreatic cancer (1).